SDC1 (syndecan 1)
Diseases named in the same sentence as SDC1 in open-access papers (continued):
Sharing a sentence is not in itself a finding about the gene and the disease.
breast carcinoma (continued). "SDC-1 expression in breast cancer stroma fibroblasts regulates cell proliferation, angiogenesis, and cell motility." (PMID 24551591, 2014). "In breast cancer, it is stated that the shed SDC-1 is derived largely from the host fibroblasts of the tumor microenvironment." (PMID 24551591, 2014). "Along the same lines, SDC1 coexpression with E-cadherin was found to be synchronously regulated during EMT in breast cancer." (PMID 25140302, 2014). "Proteolytic conversion of SDC1 from a membrane bound into a soluble molecule marks a switch from a proliferative to an invasive phenotype, with implications for breast cancer diagnostics and potential GAG-based therapies." (PMID 25140302, 2014). "The presence of syndecan-1 on mesothelioma cells is associated with favourable prognosis, while high levels of syndecan-1 in breast cancer indicate poor prognosis." (PMID 25147801, 2014). "To test this hyphothesis, we employ siRNA technology in the triple-negative MDA-MB-231 and in the hormone-receptor positive MCF-7 breast cancer cell lines to assess the molecular function of Syndecan-1." (PMID 24392029, 2013). "A candidate molecule potentially modulating all of these pathways in breast cancer is the heparan sulfate proteoglycan Syndecan-1 (CD138)." (PMID 24392029, 2013). "It has been shown that soluble and membrane-bound forms of syndecan-1 play different roles at different stages of breast cancer progression." (PMID 23844358, 2013). "Syndecan-1 has been thoroughly described as a protumorigenic agent during breast cancer development, especially in the shed form." (PMID 23984412, 2013). "One pathway, studied in human breast cancer cell lines, involves upregulation of the proteoglycan, syndecan-1 (SDC-1) by n-3 PUFA-enriched LDL." (PMID 21655218, 2011). "Publications on myeloma and mammary carcinoma models point to a syndecan-1 structure-function relationship in tumor cell adhesion and migration." (PMID 21731601, 2011). "A study of the differential roles for membrane-bound and soluble syndecan-1 in breast cancer progression has recently been published." (PMID 21731601, 2011). "Overexpression of syndecan-1 (CD138) in breast carcinoma correlates with a poor prognosis and an aggressive phenotype." (PMID 22214534, 2011). "Further investigation of the role of the heparanase–shed syndecan-1 axis in breast cancer progression should focus on disruption of heparanase function, which is likely to profoundly affect tumor growth, metastasis, and osteolysis." (PMID 20200931, 2010). "Understanding of the combined effects of heparanase, syndecan-1, and IL-8 on breast cancer progression, development of bone metastases, and activation of bone resorption is currently the focus of intense investigation in our laboratory." (PMID 20200931, 2010). "The finding that syndecan-1 shed by breast cancer cells participates in driving osteolysis adds to the growing list of important functions of this proteoglycan within the tumor microenvironment." (PMID 20200931, 2010). "We previously demonstrated that breast cancer cells expressing high levels of heparanase exhibit enhanced shedding of the syndecan-1 proteoglycan." (PMID 20200931, 2010). "These conclusions are supported by a decreased secretion of TIMP-1 in MCF-7 breast cancer cells overexpressing soluble Sdc-1 ectodomain, supporting breast cancer invasiveness." (PMID 21044331, 2010). "For example, syndecan-1 regulates the activation state of αvβ3 integrin potentially as a way for breast carcinoma cells to acquire a more invasive phenotype." (PMID 19668337, 2009). "Syndecan-1 expression in breast carcinoma specimen was observed in epithelial tumour cells, stromal component, or both." (PMID 18542065, 2008). "Because recent results are contradictory in breast carcinomas, we have re-evaluated the prognostic significance of syndecan-1 expression in a cohort of 80 patients with invasive ductal breast carcinomas." (PMID 18542065, 2008).
breast carcinoma (continued). "MCF-7, MDA-MB468 and MDA-MB231 cells, representing breast cancer cell lines of increasing dedifferentiation and metastatic capacity, were stained with antibodies specific for c-met, Sdc1 and E-cad." (PMID 17244359, 2007). "In breast cancer, increased expression of Sdc1 correlates with an unfavourable prognosis and poor response to chemotherapy." (PMID 17244359, 2007). "To characterize the interrelationship between the molecular markers investigated in this study, we performed confocal immunofluorescence microscopy colocalization experiments of c-met with Sdc1 and E-cad in human breast cancer cell lines." (PMID 17244359, 2007). "A TMA analysis of 207 human breast cancer samples by the same authors revealed that stromal Sdc1 expression correlated with vessel density and total vessel area, demonstrating a role for Sdc1 in breast tumour angiogenesis." (PMID 17244359, 2007). "In breast cancer, changes in the expression of syndecan-1, E-cadherin and c-met correlate with poor prognosis." (PMID 17244359, 2007). "In this study we characterized coexpression of the functionally linked prognostic markers Sdc1, E-cad and c-met in 200 DCIS using TMA technology and in different human breast cancer cell lines." (PMID 17244359, 2007). "The heterogeneity in Sdc1 and E-cad coexpression in breast cancer cell lines of different degrees of de-differentiation demonstrates that the concept of synchronous regulation of Sdc1 and E-cad in epithelial cells cannot be fully adapted to breast cancer." (PMID 17244359, 2007). "Coordinated regulation of E-cad and Sdc1 expression is seen during development and in mammary tumour cells subjected to antisense RNA mediated downregulation of Sdc1 or E-cad, respectively." (PMID 17244359, 2007). "Of particular interest is the SDC1 gene, which in breast cancer is expressed at high levels, and is related to an aggressive phenotype, and poor clinical behavior." (PMID 16265353, 2005). "A reasonable mechanism to account for the necessity of direct physical contact was recently proposed by Maeda and coworkers, who showed that syndecan-1 expression by mouse embryonic fibroblasts promotes proliferation of human breast cancer cell lines." (PMID 15987422, 2005). "Additionally, cell surface PGs (SDC1 and SDC4) and MMPs (MMP2, MMP7, MMP9, and MMP14) implicated in breast cancer progression were further included." (PMID 41228316, 2025). "Additionally, SDC1 expression levels were influenced by omega-3 polyunsaturated fatty acids (n-3 PUFA) in human breast cancer cells, with n-3 PUFA-enriched low-density lipoprotein (LDL) affecting SDC1-mediated biological processes." (PMID 41364407, 2025). "We further investigated and validated these findings in breast cancer, SDC1 expression was significantly correlated with stem cell markers which were mainly expressed in tumor cells and stromal cells but not immune cells in the Tumor Immune Single-cell Hub 2 (TISCH2) dataset." (PMID 41364407, 2025). "Notably, in breast cancer, SDC1 expression was negatively correlated with the scores for RNAss and positively correlated with EREG." (PMID 41364407, 2025). "Targeting SDC1 expression in tumor cells could be a potential therapeutic approach for breast cancer." (PMID 41364407, 2025). "Furthermore, we explored the role of SDC1 in breast cancer progression by knocking down its expression in breast cancer cells, which was validated in vitro and vivo." (PMID 41364407, 2025). "The validation of SDC1 expression and survival of breast cancer patients on protein level in vivo." (PMID 41364407, 2025). "The negative association of stromal SDC1 with HER2 + breast cancer suggests its significant role in immune therapy through TIL cell infiltration." (PMID 41364407, 2025). "Previously, we used the TCGA dataset to determine that SDC1 might be a prognostic marker in breast cancer through immune cell infiltration." (PMID 41364407, 2025).
breast carcinoma (continued). "Furthermore, we verified the result in breast cancer cells, indicating that higher SDC1 expression correlates with increased patient mortality, especially in the Luminal molecular subtype." (PMID 41364407, 2025). "This suggests that early breast cancer patients with positive SDC1 staining in tumor cells may require intensified chemotherapy or radiotherapy." (PMID 41364407, 2025). "Furthermore, C6S-p demonstrated the ability to bind CS-SDC1, increase SDC1 degradation, suppress macropinocytosis of breast cancer cells, and inhibit tumor growth in vivo." (PMID 38770553, 2024). "Initially, univariate Cox regression analysis revealed that 12 genes were associated with the prognosis of breast cancer, followed by LASSO analysis to derive a prognostic signature composed of 8 genes, including CERCAM, EMP1, SDC1, PRKG1, XG, TNN, WLS, and PDLIM4." (PMID 38728370, 2024). "This may suggest that a mutual regulation exists between the expression of both SDC1 and miR-10b in breast cancer." (PMID 36980680, 2023). "Thus, the HS chains attached to the SDC1 are essential for stroma-induced breast cancer development." (PMID 36980680, 2023). "Similarly, decreased SDC1 induced migratory inhibition in breast cancer cells, as demonstrated by scratch wound healing and transwell migration assays." (PMID 37056938, 2023). "Interestingly, AR and stromal SDC1 expression are altered concomitantly by subjecting breast cancer to agonists for the ER, PR, and/or AR in an animal model." (PMID 36980680, 2023). "Given the relevant role played by SDC1 in lung tumorigenesis via regulation of the exosomal miRNA pattern, we propose a similar mechanism that may exist in breast cancer." (PMID 36980680, 2023). "For example, SDC1 is overexpressed in metastatic HER2-overexpressing breast cancer." (PMID 36980680, 2023). "In the context of breast cancer, to date, dysregulations of SDC1 and SDC4 are better understood." (PMID 36980680, 2023). "Moreover, in vitro studies on breast cancer cells demonstrated the role of SDC1 in promoting tumor spreading, adhesion, proliferation, and angiogenesis." (PMID 36980680, 2023). "Data from our group revealed that the silencing of SDC1—identified as a direct downstream target of miR-10b, evidenced by a luciferase reporter assay and qPCR—promotes breast cancer cell migration and invasiveness through Rho-GTPase- and E-cadherin-dependent mechanisms." (PMID 36980680, 2023). "Clinically, different functions of Sdc-1 between cervical and breast cancer have been observed." (PMID 35155241, 2022). "In concordance, soluble Sdc-1 promoted the invasion of breast cancer cells." (PMID 35155241, 2022). "More studies are needed to explore whether SDC1 could be used as an immune therapy target in breast cancer." (PMID 35037689, 2022). "High SDC1 expression is correlated with a poor prognosis in breast cancer." (PMID 36467500, 2022). "It is possible that the release of syndecan-1 to the stromal compartment contributes to the pancreatic malignant phenotype by binding to growth factors that support cell proliferation, as happens in breast cancer." (PMID 33669066, 2021). "Increased syndecan-1 in lung microenvironments accelerated the outgrowth of mammary carcinoma metastases, whereas higher syndecan-1 levels inhibited lung carcinogenesis by regulating exosome miRNAs, and lung cancer patients with higher syndecan-1 levels were more likely have better prognoses." (PMID 34326893, 2021). "Moreover, we have previously identified Sdc-1 as part of a pro-angiogenic signature in early breast cancer." (PMID 34070901, 2021). "Treatment with zoledronate significantly downregulates the expression of SDC-1 and integrins ανβ3, ανβ5 and α5β1; this medication is thus considered to be a powerful anti-cancer agent particularly useful for the inhibition of breast cancer cell proliferation, migration and matrix invasion." (PMID 35118073, 2021).
breast carcinoma (continued). "Moreover, in breast cancer, Sdc-1 expression by stromal fibroblasts enhances tumor growth and angiogenesis." (PMID 34066023, 2021). "For example, the HA receptor CD44 is misexpressed in Sdc-1-depleted breast cancer cells, and MDA-MB-231 breast cancer cells depleted of beta4GalT-7, a biosynthetic enzyme generating the HS GAG attachment site, respond with a reduced expression of Sdc-1 and an upregulation of HA biosynthesis." (PMID 34070901, 2021). "In highly metastatic breast cancer, syndecan-1 levels are higher than in those with low metastatic character, suggesting that syndecan-1 could be a remarkable biomarker for metastatic breast cancers." (PMID 33669066, 2021). "In a Wnt-1 model of mammary carcinoma in the mouse, syndecan-1 was shown to be essential." (PMID 33561383, 2021). "Notably, the Sdc-1-dependent factors have a prognostic value in breast cancer beyond TNBC, highlighting their clinicopathological relevance." (PMID 34066023, 2021). "Overall, our data confirm a role for Sdc-1 and the HA pathway in breast cancer that together are playing an important role in tumor progression and therefore mark these molecules as attractive therapeutic targets in breast cancer." (PMID 34070901, 2021). "Finally, according to our and other results, the co-citation analysis done on the String platform showed that both Sdc-1 and HA as well as the proteins related to them participate in breast cancer biology, angiogenesis, and tumor microenvironment." (PMID 34070901, 2021). "For example, syndecan-1 acts as a tumor suppressor in breast cancer cells." (PMID 32566253, 2020). "Some of this discrepancy in the role of Sdc-1 in breast cancer development may also be due to its differential expression between cell types." (PMID 33330449, 2020). "Furthermore, SDC1 shedding has been shown to trigger a switch from a proliferative to an invasive phenotype of breast cancer cells." (PMID 32916872, 2020). "In addition, a role for syndecan-1 in polarization of T helper cell subsets has been demonstrated in human breast cancer tissue.These studies suggest that Sdc-1 has an immunosuppressive and anti-inflammatory role." (PMID 32701966, 2020). "Syndecan-1 and syndecan-4 are described as independent indicators in breast carcinomas." (PMID 32351878, 2020). "Matrigel, a reconstituted basement membrane extract from the Engelbreth-Holm-Swarm (EHS) sarcoma, is rich in basement membrane components, including the HSPG perlecan and has been used to study the invasion of breast cancer cells in response to syndecan-1 knockdown." (PMID 33163489, 2020). "Stromal, not epithelial, localization of SDC1 protein has been implicated in promoting breast density and breast cancer." (PMID 32760722, 2020). "Notably, high levels of Sdc-1 in breast cancer cells correlated with higher incidence of brain metastasis." (PMID 33330449, 2020). "Fibroblast-derived syndecan-1 is vital to promote invasion and metastasis in breast cancer cells." (PMID 32825245, 2020). "Notch pathway activation may specifically rely on the HS GAG chains of the Sdc-1, as a recent study showed that overexpression of HS-sulfotransferase enzymes regulates Notch signaling in breast cancer cells." (PMID 33330449, 2020). "However, reports on stromal syndecan-1 expression and prognosis in breast cancer are controversial and studies from an in vitro breast cancer model have suggested that syndecan-1 even directly participates in tumor cell spreading and adhesion." (PMID 29796177, 2018). "Thus, we analyzed potential mRNA expression differences of CSF-1, CSF-1R, PTPRZ1, and syndecan-1 between breast cancer samples and normal breast tissue samples from the TCGA breast cancer dataset." (PMID 29796177, 2018). "It had been published that SDC1 could be regulated by miR-10b in breast cancer, miR-143 in melanoma, miR-126 and -149 in prostate cancer, and miR-145 in urothelial carcinoma." (PMID 29963269, 2018).
breast carcinoma (continued). "Upregulation of SDC1 would promote the progression and transformation of breast cancer." (PMID 29963269, 2018). "The goal of the present study was to determine whether host Sdc1 plays a role in mammary carcinoma metastasis." (PMID 29976229, 2018). "SDC1 in breast carcinomas was correlated with poorer prognosis and an aggressive phenotype." (PMID 29963269, 2018). "This is consistent with our understanding of stromal Sdc1 activity in primary breast carcinomas." (PMID 29976229, 2018). "Syndecan-1 (Sdc1), a cell surface heparan sulfate proteoglycan normally expressed primarily by epithelia and plasma cells, is aberrantly induced in stromal fibroblasts of breast carcinomas." (PMID 29976229, 2018). "Stromal Sdc1 has been shown to promote breast carcinoma cell proliferation via paracrine pathways." (PMID 29976229, 2018). "Since tumor behavior can be highly dependent on mouse strain variations and because rate-limiting steps of metastasis may differ between carcinoma cell lines, we tested the effect of host Sdc1 in a different mouse mammary tumor metastasis model." (PMID 29976229, 2018). "Although Syndecan-1 expression is a prognostic marker for different tumor entities including breast cancer, and is a modulator of breast and prostate CSCs, its role in IBC pathogenesis is still unknown." (PMID 28270211, 2017). "MUC-1 and syndecan-1 IHC staining of breast primary carcinoma tissues, performed in four patients (number 6, 9, 11, and 13), revealed strong brown staining of in situ and infiltrating breast carcinoma cells with both MUC-1 and syndecan-1 antibodies." (PMID 28399903, 2017). "However, the distinct role of SDC1 expression in the development and metastasis of breast cancer is still unclear." (PMID 29340066, 2017). "However, future research is required to validate our findings and thus promote the clinical utility of SDC1 in breast cancer prognosis evaluation." (PMID 29340066, 2017). "SDC1 transcript expression and methylation status in human breast cancer." (PMID 29340066, 2017). "Additionally, our data provide evidence for the role played by Syndecan-1 in synchronously fine tuning multiple signaling pathways including IL-6/STAT3/gp130, inflammatory cytokines, Notch, and EGFR, implicated in breast cancer stemness." (PMID 28270211, 2017). "Depend on these findings, we demonstrated that the expression level of SDC1 might be a useful marker of the prognosis of breast cancer." (PMID 29340066, 2017). "We found that SDC1 was more frequently overexpressed in breast cancer than their normal tissues and its expression might be negatively related with some CpG sites." (PMID 29340066, 2017). "Moreover, syndecan-1 has been identified at high levels in a significant percentage of breast carcinomas and related to an aggressive phenotype and poor clinical behavior." (PMID 29340066, 2017). "Syndecan-1 acts as a tumor suppressor in MDA-MB-231 breast cancer cells." (PMID 26869927, 2016). "In addition, the highly invasive human breast cancer cells MDA-MB-231 (in contrast to the low-invasive MCF-7) can also enhance SDC1 expression, both in early-passage and senescent fibroblasts via a paracrine action of TGF-β." (PMID 27434331, 2016). "Moreover, the structurally abnormal ECM derived from Sdc1-positive fibroblasts promotes the directional migration and invasion of the breast carcinoma cells." (PMID 26909794, 2016). "SDC1, 2 and 4 have been reported to be upregulated in breast cancer." (PMID 27434331, 2016). "Moreover, zoledronic acid effectively inhibited growth, migration, and adhesion of human breast cancer cells, which was accompanied by downregulation of SDC1 and -2." (PMID 26293675, 2015). "Another study found that SDC1 expression was significantly increased in invasive breast cancer cases, suggesting that it may serve as a useful prognostic biomarker for aggressive breast cancer." (PMID 26293675, 2015). "MDA-MB-231 human breast carcinoma cells express syndecan-1 and syndecan-4." (PMID 26558271, 2015).